LINC00622 (long independently transcribed non-coding RNA 622)
Gene: Long non-coding RNA gene on chromosome 1 (119,597,702 to 119,599,271, reverse strand). Ensembl gene ENSG00000260941.
Diseases named in the same sentence as LINC00622 in open-access papers:
LINC00622 is named in the same sentence as 3 diseases in open-access papers, as found by Europe PMC text mining. Sharing a sentence is not in itself a finding about the gene and the disease. The quoted sentences say what the papers report.
cutaneous melanoma (1 paper, 2025). A primary melanoma arising from atypical melanocytes in the skin. "Our findings demonstrate that upregulated LINC00622 acts as a key regulator to transcriptionally enhance RRAGD expression and represses mTORC1-regulated autophagy by associating with BTF3 in cutaneous melanoma." (PMID 40651979, 2025). "Our findings not only demonstrated the oncogenic role of LINC00622 via RRAGD/mTORC1 axis to repress autophagic cell death in cutaneous melanoma, but also offer novel treatment targets for melanoma therapy." (PMID 40651979, 2025). "Mechanistically, LINC00622 associates with and recruits BTF3 to transcriptionally enhance RRAGD expression for activating mTORC1 and thus inhibiting autophagic cell death, which contributes to the development of cutaneous melanoma." (PMID 40651979, 2025).
melanoma (1 paper, 2025). A malignant, usually aggressive tumor composed of atypical, neoplastic melanocytes. "Loss of LINC00622 significantly increased the amount of LC3B-II and reduced P62 levels, while the formation of LC3B foci in melanoma cells increased, indicating the enhancement of autophagic flux." (PMID 40651979, 2025). "In this study, silence of LINC00622 resulted in featured autophagic cell death in melanoma cells, which can be almost fully inhibited by autophagy inhibitors (3-MA and MYH1485)." (PMID 40651979, 2025). "Functionally, LINC00622 acts as a pro-oncogenic factor to promote proliferation, colony formation, migration and invasion in melanoma while suppressing cell death." (PMID 40651979, 2025). "LINC00622 physically associates with BTF3 and binds to the RRAGD locus to transcriptionally enhance RRAGD expressions and further activate mTORC1 to inhibit autophagic cell death, which contributes to melanoma progression." (PMID 40651979, 2025). "Collectively, our study identified LINC00622 to be a highly-expressed and pro-oncogenic factor to promote the proliferation, colony formation, migration and invasiveness while repressing autophagic cell death in melanoma." (PMID 40651979, 2025). "Collectively, the higher expression and tight stage-correlating expression pattern of LINC00622 in melanoma suggests LINC00622 might be deeply involved in melanoma development and potentially play critical roles." (PMID 40651979, 2025). "Based on the screen criteria (fold change > 1.5, P < 0.05), 39 upregulated and 69 downregulated genes were identified in response to LINC00622 knockdown in SK-MEL-28 melanoma cells, while 29 upregulated and 25 downregulated genes were identified in response to LINC00622 knockdown in A375 cells." (PMID 40651979, 2025). "To validate whether LINC00622 regulates autophagy through mTORC1 pathway, we treated melanoma cells with autophagy inhibitor MHY1485 (a potent activator of mTORC1 to inhibit the fusion between autophagosomes and lysosomes) and 3-MA (a PI3K inhibitor widely used to inhibit autophagy)." (PMID 40651979, 2025). "At the same time, overexpression of LINC00622 decreased LC3B-II level and led to P62 accumulation and suppressed the formation of LC3B foci in melanoma cells." (PMID 40651979, 2025).
LINC00622 also shares sentences with these, for which no sentence is quoted: tumor (1 paper).